BMI1 (BMI1 proto-oncogene, polycomb ring finger)
Diseases named in the same sentence as BMI1 in open-access papers (continued):
Sharing a sentence is not in itself a finding about the gene and the disease.
cardiac hypertrophy (3 papers, 2017 to 2022). "Cell senescence is observed in the cardiac hypertrophy model induced by angiotensin II and in dilated cardiomyopathy caused by the silencing of Bmi1, which is verified by the elevated proportion of SA-β-gal-positive cells." (PMID 34800264, 2022). "The similar results were also reported in angiotensin II-induced cardiac hypertrophy model and dilated cardiomyopathy caused by cardiac-specific Bmi1 deletion manifested by the increased ratio of SA-β-gal positive cells." (PMID 28783759, 2017). "Ventricular wall thickening, cardiac hypertrophy and interstitial fibrosis of myocardial tissues increased in Bmi‐1–/– mice compared with WT mice." (PMID 35390228, 2022). "With Ang II treatment, Bmi‐1–/– mice showed more serious myocardial hypertrophy, aging and inflammation than WT littermates." (PMID 35390228, 2022). "NAC supplementation decreased ROS levels, ameliorated this ultrastructure, inhibited expression of renin, Ang II and p16 protein and improved cardiac function and cardiac hypertrophy in hearts from Bmi‐1–/– mice." (PMID 35390228, 2022). "To clarify whether Bmi‐1 deletion led to cardiac hypertrophy, we observed cross‐sectional areas of cardiomyocytes from Bmi‐1–/– mice." (PMID 35390228, 2022).
cholangiocarcinoma (3 papers, 2016 to 2024). A carcinoma that arises from the intrahepatic biliary tree (intrahepatic cholangiocarcinoma) or from the junction, or adjacent to the junction, of the right and left hepatic ducts (hilar cholangiocarcinoma). "Interestingly, the function of BMI1 in cholangiocarcinoma tumorigenesis and metastasis has been linked to EVs." (PMID 38254031, 2024). "In another study, immunostaining revealed that BMI1 was highly expressed in combined hepatocellular-cholangiocarcinoma and that BMI1 positivity correlated with enhanced expression of proliferation markers." (PMID 26623561, 2016). "In cholangiocarcinoma, MEG3 level was found to have been significantly decreased in cholangiocarcinoma tissues and cells as compared to that in nontumor controls and it suppressed cell proliferation and invasion via regulating Bmi1/RNF20." (PMID 31729423, 2019).
diabetes mellitus (3 papers, 2021 to 2025). A metabolic disorder characterized by abnormally high blood sugar levels due to diminished production of insulin or insulin resistance/desensitization. "Long-term diabetes may accelerate the senescence of HSPCs by reducing the expression of Bmi1." (PMID 34796200, 2021).
Hodgkins lymphoma (3 papers, 2008 to 2022). A heterogeneous group of malignant lymphoid neoplasms of B-cell origin characterized histologically by the presence of Hodgkin and Reed-Sternberg (HRS) cells in the vast majority of cases. "In epithelial cells LMP1 can up-regulate DNA methyltransferases and, in Hodgkin lymphoma cells, induce the Polycomb group protein Bmi-1." (PMID 21416002, 2009).
Immunodeficiency (3 papers, 2012 to 2024). Failure of the immune system to protect the body adequately from infection, due to the absence or insufficiency of some component process or substance. "Mouse embryos deficient in PCGF2 and PCGF4/BMI1 exhibit similar posterior transformations of the axial skeleton and display severe immune deficiency." (PMID 39337298, 2024). "Unfortunately, we were unable to maintain the AKT/Ras injected Bmi1−/− mice beyond 8 weeks post injection since these mice started to die due to infections consequent to their severe immunodeficiency." (PMID 23029524, 2012).
Infertility (3 papers, 2023 to 2026). "Male mice with BMI1 deficiency exhibit severe oligospermia and complete infertility, thus suggesting that BMI1 plays an important role in maintaining normal fertility in males." (PMID 37139440, 2023). "Previous studies have demonstrated that deleting the BMI1 gene leads to severe azoospermia, reduced testicular weight, and infertility in male mice." (PMID 37139440, 2023). "Furthermore, GC-specific depletion of Mel18, a homologue of Bmi1, leads to an early onset of infertility by ovulation defects in 10-month-old mice." (PMID 38389850, 2024). "However, deleting Mel18 in granulosa cells (GCs) did not induce infertility until its homolog, Bmi1, was deleted simultaneously." (PMID 38389850, 2024).
intestinal cancer (3 papers, 2014 to 2017). "Here we report that in the tumours of both colon/rectum and small intestine of APC∆14/+ mice, the levels of Bmi1, a well-recognized cancer stem cell marker in intestinal cancer, were increased." (PMID 28629331, 2017). "It should be stressed that the results obtained in mice indicating Lgr5+ and/or Bmi1+ crypt stem cells as the cells-of-origin of bowel cancer most likely pertain to the familiar or sporadic CRC." (PMID 24920319, 2014). "The issue of the cell of origin of intestinal cancer was further investigated in quiescent intestinal stem cells marked as Bm1-positive (Bmi1+), where transgenic ectopic expression of an oncogenic variant of β-catenin was also found to promote intestinal neoplasia in mice." (PMID 24920319, 2014). "The fact that PAK1 expression was positively correlated with the expression of Bmi1 suggests that PAK1 may play a role in the stem cell development and tumorigenesis of intestinal cancers." (PMID 28629331, 2017).
invasive breast carcinoma (3 papers, 2017 to 2020). A carcinoma that infiltrates the breast parenchyma. "Immunohistochemistry for Oct4, Sox2, Nanog, Bmi1, and Klf4 was performed in 319 cases of invasive breast cancer." (PMID 28422735, 2017).
leiomyosarcoma (3 papers, 2020 to 2022). An uncommon, aggressive malignant smooth muscle neoplasm, usually occurring in post-menopausal women. "Thus, the trial NCT03761095 is aimed at evaluating the safety of the orally active BMI1 inhibitor PTC596 (PTC Therapeutics) in combination with dacarbazine for the treatment of advanced leiomyosarcoma." (PMID 31941916, 2020).
metastatic prostate carcinoma (3 papers, 2008 to 2023). A carcinoma that arises from the prostate gland and has spread to other anatomic sites. "The researchers discovered that COMMD3: BMI1 fusion expression was significantly elevated in metastatic prostate cancer." (PMID 36776284, 2023). "COMMD3: BMI1 fusion expression and COMMD3 protein increases significantly in metastatic prostate cancer; COMMD3 activates oncogenes such as c-MYC, promotes prostate proliferation, migration and invasion; Increased COMMD3 expression is positively correlated with tumor recurrence and reduced survival." (PMID 36776284, 2023).
Obesity (3 papers, 2018 to 2024). Accumulation of substantial excess body fat. "The Bmi1 gene has a reasonably strong diagnostic performance and provides a new clinical diagnosis biomarker for obesity and associated consequences, which is confirmed by western blot and immunofluorescence staining assays." (PMID 39717104, 2024). "We found that six genes (Sacm1l, Junb, Bmi1, Erbb4, Dkc1, and Suv39h1) are neuron stress-related genes and increased in the HFD-induced mice obesity model, Bmi1gene was identified as a key genes that can reflect the pathophysiology of obesity." (PMID 39717104, 2024).
pancreatic adenocarcinoma (3 papers, 2013 to 2016). "Upon microscopic evaluation, we found that PanIN lesions and sections of human pancreatic adenocarcinoma showed marked upregulation of expression of Bmi1 when compared to normal pancreas tissues." (PMID 23437065, 2013). "In total, Bmi1 was expressed in 10/16 PanIN lesion sections and in 8/10 primary pancreatic adenocarcinomas." (PMID 23437065, 2013). "Tissue sections from 10 different primary human pancreatic adenocarcinomas, 10 normal pancreas samples, and 16 preneoplastic PanIN lesions with varying degrees of epithelial dysplasia (PanIN 1 to PanIN3) were examined for Bmi1 expression following immunohistochemical staining." (PMID 23437065, 2013). "LGR5 and BMI1 are stem-cell markers coexpressed with DCLK1 in the intestine, regulated downstream of DCLK1 following radiation injury in intestinal epithelial DCLK1 knockout mice, and markers of populations of cells with tumor stem cell activity in intestinal adenomas and pancreatic adenocarcinoma." (PMID 24885928, 2014).
pancreatic ductal adenocarcinoma (3 papers, 2013 to 2020). An infiltrating adenocarcinoma that arises from the epithelial cells of the pancreas. "We measured endogenous Bmi1 levels in primary human pancreatic ductal adenocarcinomas, pancreatic intraepithelial neoplasias (PanINs) and normal pancreas by immunohistochemistry and Western blotting." (PMID 23437065, 2013). "We hypothesized that Bmi1 plays an integral role in enhancing pancreatic tumorigenicity and the function of cancer stem cells in pancreatic ductal adenocarcinoma." (PMID 23437065, 2013).
retinoblastoma (3 papers, 2013 to 2024). A malignant tumor that originates in the nuclear layer of the retina. "This suggests a role of BMI-1 in retinoblastoma progression; further, it has the potential to be developed as a novel diagnostic marker of retinoblastoma." (PMID 23559850, 2013). "BMI-1 might be developed as a potential diagnostic marker and an important therapeutic target for retinoblastoma through specific inhibition of BMI-1 by small interfering RNAs." (PMID 23559850, 2013). "Hence, the expression of BMI-1 was shown to be significantly associated with undifferentiated retinoblastomas (p=0.05, Mann–Whitney U test)." (PMID 23559850, 2013). "The findings revealed that RKIP knockdown suppressed the role of Bmi-1 knockdown in retinoblastoma cells." (PMID 38914697, 2024). "As expected, the expression of Bmi-1 was overexpressed in retinoblastoma cell lines Y79, SO-RB50 and Weri-RB1 than that of normal retinal vascular endothelial cell line ACBRI-181." (PMID 38914697, 2024). "Bmi-1 serves as a promising therapy target for improving the efficacy of clinical treatment in retinoblastoma." (PMID 38914697, 2024). "Bmi-1 served as a potential therapeutic target for improving the efficacy of clinical treatment in retinoblastoma." (PMID 38914697, 2024). "The functions of Bmi-1 knockdown on retinoblastoma cells were blocked by RKIP knockdown, but promoted by RKIP." (PMID 38914697, 2024). "In common with other cancer cells, our findings reveal that BMI-1 is important for retinoblastoma cell growth." (PMID 23559850, 2013). "In conclusion, we identified significant BMI-1 upregulation in retinoblastomas of low differentiation status and invasion to posterior tissues." (PMID 23559850, 2013). "Nuclear BMI-1 staining was present in the majority of retinoblastoma specimens (33/34 tumors, 97.1%)." (PMID 23559850, 2013). "Our finding of elevated BMI-1 expression, particularly in undifferentiated retinoblastomas, further indicates the self-renewal capacity and extensive proliferation of these tumor cells." (PMID 23559850, 2013). "In this study, we investigated BMI-1 expression and the clinicopathological parameters of human retinoblastomas." (PMID 23559850, 2013). "In this study, we detected BMI-1 upregulation in undifferentiated human retinoblastomas when compared to differentiated cases (p=0.05)." (PMID 23559850, 2013). "Human retinoblastoma Y79 cells were transfected with pCMV-HA/BMI-1 for BMI-1 overexpression or by pSuper-BMI-1-si for specific BMI-1 suppression." (PMID 23559850, 2013). "In this study, RNA interference technology was used to suppress the expression of Bmi-1, and to observe the inhibitory effect of Bmi-1 siRNA on the expression of Bmi-1 gene in human retinoblastoma cells and its effect on cell proliferation, migration, invasion and apoptosis." (PMID 38914697, 2024). "Bmi-1 promoted retinoblastoma cell progression through regulating the expression of RKIP." (PMID 38914697, 2024). "The purpose of our study was to explore the role of Bmi-1 in retinoblastoma." (PMID 38914697, 2024). "All the findings revealed the functions of Bmi-1/RKIP axis in retinoblastoma tumorigenesis." (PMID 38914697, 2024). "BMI-1 expression and clinicopathological features of retinoblastomas." (PMID 23559850, 2013). "We studied BMI-1 expression in 27 retinal tissues adjacent to retinoblastoma." (PMID 23559850, 2013). "In this study, we showed that BMI-1, a polycomb group transcription factor and an oncogene, plays a crucial role in retinoblastoma proliferation, and may contribute to its malignancy." (PMID 23559850, 2013). "For instance, numerous studies showed that the presence of many dysregulation CRs (e.g., UHRF1, DNMT1, EZH2, BMI1 and HELLS) might lead to an abnormal epigenetic landscape in retinoblastoma (RB), which might be associated with tumorigenesis and malignant progression." (PMID 36318256, 2023).
retinoblastoma (continued). "Hence, our findings indicate that BMI-1 might play an important role in the development of and malignancy of human retinoblastoma." (PMID 23559850, 2013). "Bmi-1 was over expressed, and RKIP was low expressed in retinoblastoma cells." (PMID 38914697, 2024).
synovial sarcoma (3 papers, 2009 to 2016). "EGR1 is repressed by the SS18-SSX fusion protein in synovial sarcoma in that SS18-SSX recruits PcG proteins, including EZH2 and Bmi1, to the EGR1 promoter and correlates with H3K27me338." (PMID 27125524, 2016).
T cell lymphoma (3 papers, 2010 to 2021). "A RING finger domain mutant of Bmi1 (the mouse homologue of human BMI1) was shown to be ineffective in collaborating with c-myc to induce B- and T- cell lymphomas." (PMID 20569464, 2010). "The poor prognosis of T cell lymphoma patients with high BMI1 expression suggest that activated BMI1 might be involved in the progression to a high-risk phenotype." (PMID 28412742, 2017). "Interestingly, the PS region of Bmi1 was not required to induce B- and T- cell lymphomas in the mouse model." (PMID 20569464, 2010). "Direct binding of MALAT1 to the PRC2 components (EZH2 and SUZ12) was observed in a T cell lymphoma cell line; however, no direct binding of MALAT1 with H3K27me3 and BMI1 (a PRC1 component) was observed." (PMID 28412742, 2017). "In the non-treated cell line derived from a patient with T cell lymphoma (HH cells), baseline protein expression levels of PRC-related markers, especially EZH2, SUZ12, BMI1, and H3K27me3, were very strong." (PMID 28412742, 2017).
age (2 papers, 2010 to 2019). A temporal measurement of the time period elapsed since an identifiable point in the life cycle of an organism. "As the deletion of the PS domain of BMI1 results in a stable and constitutively active BMI1, and leads to a robust downregulation of p16INK4a, we speculate that the PS region of BMI1 could also be targeted for the development of treatment strategies for age-related pathologies." (PMID 20569464, 2010).
anemia (2 papers, 2014 to 2021). A reduction in the number of red blood cells, the amount of hemoglobin, and/or the volume of packed red blood cells. "Bmi1 has been associated with progressive loss of proliferative capacity of hematopoietic stem cells and anemia." (PMID 25481243, 2014). "Interestingly, histological analysis of moribund Bmi-1-/- mice revealed pneumonia, anemia, and opportunistic infections of the intestinal tract." (PMID 33465144, 2021).
astrocytic tumor (2 papers, 2015 to 2025). A glial tumor of the brain or spinal cord showing astrocytic differentiation. "Therefore, the present study aimed to evaluate the expression and methylation profiles of the genes CDKN2A, CDKN2B, CDC6, Bmi-1, CCND1, and RB1 in astrocytic tumors in the northern region of Brazil." (PMID 26317630, 2015).
Azoospermia (2 papers, 2020 to 2023). Absence of any measurable level of sperm,whereby spermatozoa cannot be observed even after centrifugation of the semen pellet. "Some target genes of the downregulated miRNAs, such as ACVR2A, CCND1, CCNE2, HMGA2, BMI1, NR2C2 and BCL2, have been associated with gonadal development, and germ cell maintenance through different pathways which could be relevant to the molecular mechanisms affected in KS patients with azoospermia." (PMID 32651451, 2020).
benign prostatic hyperplasia (2 papers, 2013 to 2020). A non-cancerous nodular enlargement of the prostate gland. "The clinical significance of BMI1 as a biomarker could be ascertained from observation that CaP cells secrete this protein in higher levels than cells representative of benign prostatic hyperplasia (BPH)." (PMID 23308129, 2013). "However, to what extent does Bmi-1 affect prostatic hyperplasia is unknown." (PMID 33584271, 2020). "Interestingly, BMI1 expression was found to be very low in prostate epithelial cells representing benign prostatic hyperplasia (BPH) condition (data not shown)." (PMID 23308129, 2013).
dementia (2 papers, 2021 to 2023). Loss of intellectual abilities interfering with an individual's social and occupational functions. "Furthermore, recent studies have shown that BMI1 expression is reduced in AD brains but not in other types of dementia, such as frontotemporal dementia or dementia with Lewy bodies." (PMID 34610832, 2021).
diffuse intrinsic pontine glioma (2 papers, 2017 to 2025). A neuroglial tumor that arises from the middle portion of the brain stem. "In the present study, we demonstrate that the phosphorylation of BMI-1 in diffuse intrinsic pontine glioma (DIPG) cells occurs in M phase and that it triggers simultaneous translocation of the phosphorylated BMI-1 to the cytoplasm." (PMID 41455108, 2025).
fibrosarcoma (2 papers, 2007 to 2019). A malignant mesenchymal fibroblastic neoplasm affecting the soft tissue and bone. "Golub-score analysis identified a relatively poor discriminatory signal of 200 genes for the fibrosarcomas, which regardless of high FDR contained several of the upregulated genes previously associated with fibrosarcoma, e.g. BMI1, H1F0, LEF1, RBM4, ITM2A, IGFBP2 and PTGS2." (PMID 17359542, 2007).
follicular lymphoma (2 papers, 2016 to 2018). Follicular lymphoma is a form of non-Hodgkin lymphoma characterized by a proliferation of B cells whose nodular structure of follicular architecture is preserved. "This is in accordance to data already reported in literature, where BMI1 positivity has been described in AML blasts, in Ph'-negative chronic myeloproliferative neoplasias, and in follicular lymphoma." (PMID 30574454, 2018).
gastroesophageal reflux (2 papers, 2015 to 2020). "High CA9 expression may be related to the acidic environment caused by gastroesophageal reflux disease in the gastroesophageal junction and associated with tumorigenesis through BMI1, MCM4 and MCM7." (PMID 26156831, 2015).
Hyperglycemia (2 papers, 2019 to 2022). An increased concentration of glucose in the blood. "In hyperglycemia conditions, the downregulation of BMI1 expression caused a significant increase in PHLPP1 and PHLPP2 in both cell lines." (PMID 36497428, 2022). "Thus, it seems that the decrease in AKT phosphorylation in BMI-1-depleted cells may be caused by the reduced expression of PHLPPs but only in hyperglycemia conditions." (PMID 36497428, 2022). "Glucose and insulin impact on the BMI-1 dependent regulation of PHLPP-analyzed cells with the downregulation of BMI-1 expression in hypo-, normo-, and hyperglycemia conditions and stimulation by insulin." (PMID 36497428, 2022). "There was a significant inverse correlation between BMI-1 expression and PHLPPs expression but only in hyperglycemia conditions." (PMID 36497428, 2022). "Hyperglycemia increased Bmi1 and GATA2 level, and decrease MICA/B and p-AMPK in vivo, as determined with IHC assessment." (PMID 31088566, 2019). "The explanation of BMI-1’s role in insulin signaling and PHLPP regulation may contribute to a better understanding of mechanisms underlying hyperglycemia and cancer progression." (PMID 36497428, 2022).